CCND1 (cyclin D1)
Diseases named in the same sentence as CCND1 in open-access papers (continued):
Sharing a sentence is not in itself a finding about the gene and the disease.
type 2 diabetes (9 papers, 2008 to 2022). "Others have described that the CDKN2B-AS1 (antisense 1) variant is associated with coronary artery disease and type 2 diabetes, and variants in CCND1 have been associated in GWAS with type 2 diabetes, hemoglobin A1c, and BMI." (PMID 35730565, 2022). "The current study highlights a significant reduction of PPAR-γ and Cyclin-D1 levels in type 2 diabetic patients, an effect that was successfully reversed of camel milk colustrum containing Lf." (PMID 30534206, 2018). "In our study, we found that PCNA and Cyclin D1 protein expression increased, whereas P27 expression decreased in renal arteries from type 2 diabetes patients." (PMID 27252826, 2016). "A considerable decrease was observed in the protein expression levels of Runx2, β-catenin, p-β-catenin, cyclin D1 and c-myc in BMSCs from type 2 diabetic rats compared with BMSCs from normal rats (p<0.05)." (PMID 26296196, 2015). "INSR gene is involved in 12 pathways of which, Type II diabetes mellitus, PI3K-Akt signaling pathway, Insulin signaling pathway (FDR < 0.05) are prominent related to Type 2 Diabetes whereas CCND1 is involved in Jak-STAT signalling pathway apart from PI3K-Akt signaling pathway." (PMID 28761062, 2017). "In EPCs isolated from type 2 diabetic patients there is an inhibition of STAT5/PPARγ transcriptional complex, leading to inactivation of Cyclin D1 and cell cycle arrest." (PMID 36176980, 2022).
atherosclerosis (8 papers, 2016 to 2024). A disease characterized by the build-up of fatty material and calcium deposition in the arterial wall resulting in partial or complete occlusion of the arterial lumen. "In conclusion, the network pharmacology identified 17 potential therapeutic targets of ginsenoside Rb1 in treating atherosclerosis and CCND1 has the highest binding energy with ginsenoside Rb1." (PMID 38546402, 2024). "Our molecular docking results showed that ginsenoside Rb1 had good binding interactions with CCND1, suggesting that ginsenoside Rb1 stably combined with CCND1 for attenuating atherosclerosis." (PMID 38546402, 2024). "Previous researches have suggested that NR4A3 acts as a pro‐proliferation factor involved in atherosclerosis by enhancing cell viability and mediating cell cycle (inducing cyclin D1 and D2 expression)." (PMID 33942991, 2021). "In summary, this finding states the vital role of the circCHFR/miR-370/FOXO1/Cyclin D1 axis and provides a profound understanding about the circRNA in smooth muscle cells and atherosclerosis." (PMID 31048182, 2019). "Thus, an association has been established between several stretch-specific miR-1183 targets and cardiac remodeling, such as: KCNA3 with diabetic cardiomyopathy, MED23 with CHD, SAMSN1 with atherosclerosis, CCND1 with myocardial ischemia-reperfusion injury, and MCOLN3 with atrial fibrillation." (PMID 35805966, 2022). "In this study, we demonstrated that Kiom-18, a novel composition of C. cassia, P. densiflora, C. longa and G. glabra, prevents atherosclerosis through the anti-proliferative effect on VSMCs via the regulation of cell cycle-related proteins such as CDK2, CDK4, cyclin D1, cyclin E1, Rb, and PCNA." (PMID 27465365, 2016).
cardiac hypertrophy (8 papers, 2014 to 2025). "CCND1 has been implicated in the regulation of the cell cycle and cardiac hypertrophy in HF, and HIF1A is known to be involved in angiogenesis and tissue remodeling under hypoxic conditions, both of which are essential processes in HF progression." (PMID 40818967, 2025). "The DEGs associated with cardiac hypertrophy were screened via bioinformatics analysis, and eight hub genes were identified, including Akt1, Lox, Timp1, Col1al, Spp1, Ccnd1, Mmp3, and Egfr, which might be a new target for the identification of cardiac hypertrophy." (PMID 36046382, 2022). "Furthermore, several studies have suggested that increased cyclin D1 expression is associated with renal and cardiac hypertrophy, which may be attributed to increased stabilisation of p21." (PMID 26464852, 2014). "We have shown that statin prevents angiotensin II‐induced cardiac hypertrophy via inhibition of cyclin D1 expression and attenuation of Rho kinase activity." (PMID 29744294, 2018). "miR-93 suppresses cardiac hypertrophy responses and targets cyclin D1 gene (CCND1)." (PMID 38256030, 2024). "DUSP1, CCND1, STAT3, and THBS1 play important roles in the pathological process of hypertrophic cardiomyopathy (HCM), regulating myocardial hypertrophy, fibrosis, and cardiac remodelling through a complex signalling network." (PMID 40427439, 2025). "In another study, a comprehensive analysis of transcriptomic data from HF patients and animal models revealed several key genes, such as MYC, CCND1, and HIF1A, which were found to play central roles in regulating cardiac hypertrophy and fibrosis." (PMID 40818967, 2025). "To further investigate the effect of TP on the protein expression of cell cycle regulators in NRVMs, we examined the expression of several cell cycle-specific proteins, cyclin D1, CDK4 and 6, and P21, on cardiac hypertrophy progression." (PMID 33013405, 2020). "While individual studies have shown that CCND1 and HIF1A are crucial players in cell proliferation and migration, particularly in cardiac hypertrophy and vascular remodeling, the interaction of these genes within the PI3K/AKT pathway in HF is still not fully understood." (PMID 40818967, 2025).
hepatoblastoma (8 papers, 2012 to 2023). Hepatoblastoma (HB) is a malignant hepatic tumor and is the most common pediatric liver cancer. "Later, the same team studied 84 children with hepatoblastoma and demonstrated that a polymorphism (G to A) at codon 242 of CCND1, a gene encoding cyclin D1, was associated with the age of disease onset." (PMID 35986847, 2022). "Wnt/β-catenin activation has been found to be associated with increases in c-myc and cyclin D1 staining in tumours of patients with hepatoblastoma." (PMID 22506042, 2012). "Overexpression of CCND1 in a patient with hepatoblastoma was considered a good prognostic indicator." (PMID 28007021, 2016). "Results of a previous study using HCC cell lines (Hep3B, HLF, HLE, PLC/PRF/5, and Huh-7) and the hepatoblastoma cell line Huh-6 treated with Sora, revealed that Sora induced the downregulation of cyclin D1 expression, and induced cell cycle suppression and apoptosis." (PMID 37365571, 2023). "Furthermore in chemical-induced hepatoblastoma model, an increase in intranuclear localization of β-catenin was correlated with increase in the expression of cyclin D1 and c-Jun, which are target genes of β-catenin and crucial in cellular proliferation." (PMID 31511432, 2019). "Transfection of hepatoblastoma cell lines (Huh-6 and HepG2) with siRNA of frizzled receptors (receptor of Wnt ligands) is shown to inhibit Wnt signaling, decrease the expression of frizzled receptor genes, cyclin D1 and suppress the cellular proliferation." (PMID 31511432, 2019). "CCND1 was identified as the core gene in the β-catenin/LEF pathway, which is relevant to hepatoblastoma’s development." (PMID 34367972, 2021). "Furthermore, activation of cancer-related processes through Myc and Ccnd1 and matrix metalloproteinases have been identified and increased β-catenin expression has been reported in HCC and aggressive hepatoblastomas." (PMID 27777588, 2016).
Hyperinsulinemia (8 papers, 2019 to 2025). An increased concentration of insulin in the blood. "Interestingly, high levels of cyclin D1 (encoded by CCND1), an important regulator of cell cycle progression, were detected in obese individuals with hyperinsulinemia as well as adipocytes from individuals with T2D." (PMID 37317964, 2023). "Overall, these findings support the link between hyperinsulinemia, Cyclin D1 and senescence and identify a mechanism by which hyperinsulinemic individuals can induce a senescent response." (PMID 35872305, 2022). "Cyclin D1 (CCND1), a downstream effector of the mitogenic insulin-signaling pathway, plays a key role in mediating the hyperinsulinemia-activated endoreplication and subsequent senescence in mature adipocytes." (PMID 35872305, 2022). "Moreover, high levels of cyclin D1 (encoded by CCND1), an important regulator of cell cycle progression, was detected in obese individuals with hyperinsulinemia." (PMID 37195383, 2023). "The size and DNA content of senescent cells exposed to hyperinsulinemia were significantly increased, indicating enhanced endoreplication and suggesting a mechanism by which insulin can sustain cellular stress by enhancing Cyclin D1 expression." (PMID 35872305, 2022). "This insulin-inducing effect on CCND1 in DOX-treated cells was also confirmed by immunostaining and provide additional support to the notion that chronic hyperinsulinemia aggravates hepatocyte senescence acting through insulin-activated cell cycle dynamics." (PMID 35872305, 2022).
Hypertension (8 papers, 2015 to 2021). The presence of chronic increased pressure in the systemic arterial system. "Herein, we provide evidence showing that NF-κB and cyclin D1 activation are important for CH-induced PA remodeling and hypertension." (PMID 32669538, 2020).
intestinal tumors (8 papers, 2013 to 2024). "We observed increased accumulation of the transcription factor TCF4 and its co-activator β-catenin as well as their downstream oncogenic target protein cyclin-D1 in 56Fe ion-induced intestinal tumors." (PMID 26500891, 2015). "Remarkably, the lesions of Apcmin/+Vdr−/− mice showed higher β-catenin nuclear levels and expression of its targets genes Ccnd1/Cyclin D1 and Lef1 than those of Apcmin/+Vdr+/+ mice, suggesting that Vdr deletion promotes intestinal tumor growth through the activation of the Wnt/β-catenin pathway." (PMID 24202444, 2013). "Likewise, the antitumor action of 1,25(OH)2D3 on chemically induced mouse intestinal tumors is concomitant with increased expression of E-cadherin and the inhibition of β-catenin/TCF target genes such as c-Myc and Ccnd1/cyclin D1 in the intestinal crypts of these animals." (PMID 33227961, 2020).
metastatic carcinoma (8 papers, 2015 to 2025). A carcinoma which has spread from the original site of growth to another anatomic site. "In metastatic carcinoma CaOV-3, both ObR antagonists had an inhibitory effect on the cdk2/cyclin D1 complex, while in serous carcinoma, OVCAR-3, they only had an effect on cdk2 and cdk4 protein expression." (PMID 27480179, 2016). "All the metastatic carcinomas showed nuclear cyclin D1 immunolabelling with 69% depicting intense, grade 3 diffuse nuclear staining." (PMID 25907675, 2015).
plasma cell neoplasm (8 papers, 2012 to 2025). A clonal proliferation of immunoglobulin-secreting plasma cells. "The NF-κB2 mutant p80HT promotes the development of plasma cell tumors by transcriptional activation of genes critical for the generation, proliferation and survival of plasma cells, including cyclin D1, cyclin D2, Blimp1, survivin, IL-10 and IL-15." (PMID 22642622, 2012). "Cyclin D1 positivity, although characteristic of MCL, may be expressed in plasma cell neoplasms, contributing to diagnostic error." (PMID 40821198, 2025). "In addition to Cyclin D1, the use of markers such as CD138, CD38, and light chain restriction by immunohistochemistry and flow cytometry is critical in characterizing plasma cell disorders." (PMID 40821198, 2025).
salivary gland tumors (8 papers, 2015 to 2025). "The second most common aberrations involved the cyclin pathway (CCND1, CDK4/6 or CDKN2A/B), which was abnormal in 26.5% of patients (31/117) with salivary gland tumors." (PMID 26247885, 2015). "They reported that expression of cyclin D1, CDK4 and CDKN2A were significantly higher in malignant salivary gland tumors (including adenoid cystic carcinoma and mucoepidermoid carcinoma) when compared to normal salivary gland." (PMID 26247885, 2015).
small cell lung carcinoma (8 papers, 2011 to 2025). Small cell lung cancer (SCLC) is a highly aggressive malignant neoplasm, accounting for 10-15% of lung cancer cases, characterized byrapid growth, and early metastasis. "Epibrassinolide reduced lysate β-catenin levels and the expression of pathway target genes such as c-Myc, CCND1, Sox9, c-Jun, Survivin, MMP1, MMP7, and mPar in NCI-H69 and a multi-drug-resistant VPA17 small-cell lung carcinoma line." (PMID 40427472, 2025).
thyroid (8 papers, 2011 to 2021). "We also found that the immunostaining score of cyclin D1 at 15.7% predicted a thyroid malignancy with a sensitivity of 86.4% and specificity of 80.5% in histological analysis (P < 0.0001)." (PMID 30885146, 2019). "Expression of cyclin D1 in thyroid nodules was determined by immunohistochemistry using both surgical specimens and their cytological specimens." (PMID 30885146, 2019). "Based on our findings in the current study, we found that cyclin D1 immunostaining provided a powerful, robust cytology-based thyroid diagnosis." (PMID 30885146, 2019). "Our present results, which have focused on PIN1 mRNA expression, as well as our earlier data, concerning cyclin D1 mRNA overexpression in thyroid malignancy, may suggest that one of the major regulatory mechanisms in cell transformation in thyroid carcinogenesis is PIN1 gene activity." (PMID 21219594, 2011). "Immunohistochemical profiles were studied by markers previously found to be related to thyroid malignancy such as CK19, galectin-3, HBME-1, and cyclin D1." (PMID 33991306, 2021). "Nevertheless, the role of CCND1 in thyroid tumorigenesis has been poorly investigated, except for recent papers showing CCND1 as a direct target of deregulated miRNAs and long non-coding RNAs." (PMID 31947935, 2020).
bladder urothelial carcinoma (7 papers, 1999 to 2023). "Further, the distinctly different prognostic roles of cyclin D1 in superficial and muscle-invasive bladder cancers reinforce the concept that urothelial bladder cancer comprises two different diseases with distinct underlying molecular mechanisms." (PMID 36675501, 2023). "Using immunohistochemistry, we examined 79 invasive transitional cell carcinomas of the urinary bladder treated by cystectomy, for loss of Rb or p16INK4a protein and for cyclin D1 overexpression." (PMID 10376969, 1999). "CCND1 and expression of CyclinD1 were evaluated by fluorescence in situ hybridization and immunohistochemistry on patient tumor biopsies obtained from node-positive urothelial bladder cancers." (PMID 37835580, 2023). "Correspondingly, proteins related to cell cycle such as CDK4, CDK6 and Cyclin D1 were obviously diminished after specific siRNA treatment, which is consistent with the phenomenon that bladder urothelial carcinoma cells are largely arrested in the G1 phase." (PMID 33980246, 2021). "A large study which assessed cyclin D1 localisation was performed with 150 transitional cell carcinomas of the bladder, wherein cytoplasmic cyclin D1 increased with disease progression and correlated with decreased survival." (PMID 17375037, 2007).
COVID-19 (7 papers, 2021 to 2024). A disease caused by infection with severe acute respiratory syndrome coronavirus 2. "Exposure to CS or nicotine upregulated many genes within AGE-RAGE signalling with high confidence, including CCND1, CXCL8, HRAS, IL6, KRAS and TNF, suggesting that smokers have a hyperactive AGE-RAGE and are therefore more at risk of severe COVID-19." (PMID 38991709, 2024). "A network pharmacology study showed that quercetin, luteolin, and baicalein were the main compounds of Huopu Xialing Decoction, which might regulate multiple signaling pathways targeting Akt1, MAPK1, cyclin D1 (CCND1), and caspase-8, thus played a therapeutic role on COVID-19." (PMID 34861881, 2021). "Using the network pharmacology approach, we identified two clusters of genes involved in immune response (IL1A, IL2, and IL6R) and cell proliferation (CCND1, PPARG, and EGFR) mediated by biochanin A in CRC/COVID-19 condition." (PMID 34931923, 2021). "In our analysis, we identified two target gene clusters of biochanin A including inflammatory genes (IL1A, IL2, and IL6R) and cell proliferation genes (CCND1, PPARG, and EGFR) relevant to the treatment of CRC/COVID-19." (PMID 34931923, 2021). "We have identified gene clusters associated with CRC, COVID-19, and biochanin A. Bioinformatic analysis further showed the involvement of six core targets of biochanin A in the treatment of CRC/COVID-19, including EGFR, CCND1, IL2, IL1A, IL6R, and PPARG." (PMID 34931923, 2021). "Our results showed 13 potential targets of biochanin A; the molecular interaction network analysis using Cytoscape further highlighted the involvement of six core targets of biochanin A, EGFR, CCND1, IL2, IL1A, IL6R, and PPARG, for the treatment of CRC/COVID-19." (PMID 34931923, 2021).